CDK4 (cyclin dependent kinase 4)
Diseases named in the same sentence as CDK4 in open-access papers (continued):
Sharing a sentence is not in itself a finding about the gene and the disease.
melanoma (continued). "In addition to BRAF mutant melanoma, enhanced mTORC1 activity has also been reported to associate with acquired resistance to combined inhibition of CDK4/6 and MEK in NRAS-mutant melanomas." (PMID 34304249, 2021). "Even though solar ultraviolet exposure is the main environmental risk factor for cutaneous melanoma development, there are still genetic susceptibility factors, such as germline mutations in p16 or CDK4, and genesis of melanoma, such as the main genetic drivers BRAF, NF1 and NRAS mutations." (PMID 32333246, 2020). "In 1995, a mutated CDK4 was found in cultured melanoma cells and metastatic tissue." (PMID 31717496, 2019). "Rare germline mutations in CDK4 at position 24 predispose to melanoma susceptibility." (PMID 31795494, 2019). "These activating mutations of CDK4 (R24C and R24H), in the p16INK4a binding domain, as well as inhibitory mutations in p16INK4a in the germline lead to a 50-fold increase in the risk of developing melanoma." (PMID 30858922, 2019). "Currently, the National Comprehensive Cancer Network (NCCN) reports that BAP1 testing may be warranted in specific cases, along with testing for other melanoma-predisposing genes like CDK4, MITF and TERT." (PMID 31382929, 2019). "Furthermore, the deregulation of pRb pathway due to CDKN2A or CDK4 gene mutations is particularly frequent in melanomas arising from skin chronically exposed to sun." (PMID 31142321, 2019). "MAPK pathway activation and cell cycle dysregulation are general hallmarks of melanoma resulting from aberrations in cell proliferation, deficiency of the retinoblastoma protein (pRb), mutations in CDK4, and overexpression of cyclin D1 following resistance to BRAF inhibition." (PMID 29541385, 2018). "Variants in the CDK4 gene have been observed in only a small number of melanoma families." (PMID 29774366, 2018). "Considering the extremely rare coexistence of MPM and OCA, we decided to analyze in the two indexes affected by both conditions, over CDKN2A and CDK4 alterations, a pattern of other genes involved in melanoma predisposition and pathogenesis, in skin/hair pigmentation and in immune pathways." (PMID 27776349, 2017). "The CDK4 pathway comprising of signaling components like p16INK4a-cyclin D-CDK4/6-retinoblastoma is known to be altered in 90% of human melanomas, while 15–20% of melanoma cases show mutations in the NRAS gene." (PMID 29121869, 2017). "The frequent loss of p16INK4a in melanomas suggests that CDK4 activity may be unchecked in melanoma and may play a role in promoting uncontrolled proliferation of melanoma cells." (PMID 26201960, 2015). "The melanoma-associated Cdk4 R24C mutation disrupts p16 binding." (PMID 25481981, 2015). "Familial melanoma can be caused by mutations in p16 or Cdk4." (PMID 25481981, 2015). "Mutations in the CDKN2A and CDK4 genes predispose to melanoma." (PMID 25780468, 2014). "Additionally, a small number of melanoma pedigrees have been found to carry mutations of the CDK4 gene, at the binding site for the CDKN2A gene product." (PMID 25780468, 2014). "CDK4, a melanoma susceptibility gene, has also been shown to be a target of MITF." (PMID 22848417, 2012). "Germline mutations in CDKN2A and CDK4 have been linked to familial melanoma, however mutations in both of these genes have been infrequently reported in young onset melanoma." (PMID 21915125, 2011).
melanoma (continued). "A second melanoma susceptibility gene, CDK4, was identified by candidate gene approach." (PMID 24281082, 2010). "CDK4 is a rare high-penetrance melanoma predisposition gene." (PMID 19828018, 2009). "Indeed, only three melanoma families worldwide are carriers of mutations in CDK4 (Arg24Cys and Arg24His)." (PMID 19828018, 2009). "CDK4 germline mutations have been identified in eight melanoma-prone families worldwide (Zuo etal., 1996; Soufir etal., 1998; Molven etal., 2005; Pjanova etal., 2007; Soufir etal., 2007) and these disrupt the interaction between p16INK4a and CDK4 (Zuo etal., 1996)." (PMID 18843795, 2008). "Germline mutations in CDK4 were detected in three melanoma families." (PMID 15928671, 2005). "Therefore, the specific aim of this study was to assess the prevalence of INK4a-ARF and Cdk4 mutations among different subgroups of patients with a possible hereditary predisposition to melanoma." (PMID 14735200, 2004). "In contrast, mutations of Cdk4 appear to be a rare cause of inherited susceptibility to melanoma." (PMID 14735200, 2004). "Physical interaction between CDKN2A/p16 and CDK4 proteins regulates the cell cycle progression through the G1 phase and dysfunction of these proteins by gene mutation is implicated in genetic predisposition to melanoma." (PMID 11556834, 2001). "Our results, obtained in a heterogeneous group of families, support the view that inactivating mutations of CDKN2A contribute to melanoma susceptibility more than activating mutations of CDK4 and that other genetic factors must be responsible for melanoma clustering in a high proportion of families." (PMID 11556834, 2001). "In 2021, it was proposed that cyclin-dependent kinase 4 and 6 (CDK4/6) inhibitors could be utilized with success for breast cancer, in response to metabolic reprogramming observed in melanoma following standard BRAF/MEK inhibition implicated in both therapeutic response and resistance." (PMID 40872623, 2025). "We detected clonal mutations of all types that affected genes known to contribute to melanoma initiation, including hotspot SNVs in Kras and Gnaq, SNVs in frequently mutated sites of Sf3b1 and Tfap2a, homozygous deletion of Cdkn2a, and amplifications of Met, Braf, Mitf, Kras, Cdk4, and Erbb3." (PMID 40950124, 2025). "In previous work, we identified the oncogenic Q209L mutation in the Hgf-Cdk4 melanoma cell line HCmel12, raising the question of whether Gnaq mutations are a frequent early oncogenic driver event during melanoma evolution in the Hgf-Cdk4 melanoma model." (PMID 38360887, 2024). "Also, CDK4 can be found mutated in about 1.5% of melanoma-prone families." (PMID 38730639, 2024). "In addition, in vitro studies have shown that CDKN2A mutated melanomas may benefit from CDK4/6 inhibitors, and this therapy may be beneficial for patients with acquired resistance to BRAF/MEK inhibitors." (PMID 37373134, 2023). "Similar results have been observed in CDK4/6 inhibitor (abemaciclib) combined with MEK1/2 inhibitor (trametinib) in A375 melanoma cell line (NRAS wild‐type)." (PMID 41492362, 2026). "Nonetheless, a modest set of studies has combined ICIs with CDK4/6 inhibitors especially after the emergence of refractory cases despite the initial success of immunotherapies in advanced melanoma." (PMID 40856900, 2025). "Expanding the study to other tumor types reliant on CDK4/6 signaling, such as melanoma, lung cancer, and colorectal cancer, will also be important to fully realize LA-CB1’s clinical potential." (PMID 40038413, 2025). "In this contest, CDK4 variants are linked to FAMMM syndrome (Familial Atypical Multiple Mole Melanoma), which is characterized by multiple nevi, cutaneous and uveal malignant melanomas, and a high risk of pancreatic carcinoma." (PMID 40558591, 2025). "Functionally, knocking down GAS5 in melanoma cells accelerates G1/S progression through increases in cyclin D1, CDK4, and p27; boosts viability; and blunts apoptosis via increased expression of Bcl-2." (PMID 41463281, 2025).
melanoma (continued). "Alterations in the CDKN2A gene or the p16-cyclin D-CDK4/6-retinoblastoma protein pathway (CDK4 pathway) have been found in virtually all melanoma cell lines." (PMID 40076927, 2025). "We also demonstrated that blocking CDK2 activity enhanced the response to CDK4/6 inhibitors in these melanoma models." (PMID 40904502, 2025). "In melanoma, three studies that explored resistance to combined CDK4/6is and MEK inhibition found that resistant tumors were frequently characterized by the activation of the PI3K pathway." (PMID 40282469, 2025). "As a result, the Notch pathway is activated, leading to the transcription of c-MYC, proliferating cell nuclear antigen (PCNA), and CDK4, which are involved in melanoma progression." (PMID 41463281, 2025). "Until recently, the primary genes that were recognized and clinically evaluated for predisposition to melanoma were CDKN2A/ARF (cyclin-dependent kinase inhibitor 2A) and its associated gene CDK4 (cyclin-dependent kinase 4)." (PMID 40558591, 2025). "Many preclinical studies have shown that CDK4/6 inhibitors can effectively induce cell cycle arrest in melanoma cells, providing a strong foundation for their clinical evaluation." (PMID 40282469, 2025). "Multigene panel testing, including genes like CDKN2A, CDK4, BAP1, POT1, ACD, and TERF2IP, enhances the detection of hereditary melanoma risk." (PMID 39941357, 2025). "Additional studies have demonstrated a role for CDK2 activity as a mechanism of resistance to CDK4/6is in melanoma." (PMID 40282469, 2025). "The main objective of the study described in this report is to develop new approaches to improve the efficacy of CDK4/6 inhibitors for the treatment of melanoma." (PMID 40904502, 2025). "Given that the MAPK pathway is frequently activated in melanoma through mutations in BRAF, combining CDK4/6is with BRAF inhibitors (BRAFis) and MEK inhibitors (MEKis) offered a promising therapeutic strategy." (PMID 40282469, 2025). "Among the 161 CDKN2A/CDK4/BAP1-negative melanoma families included in this cohort, only one likely PV in POT1 (c.676C > A, p.His226Asn) was identified (0.6%)." (PMID 40851494, 2025). "CCND1 and CDK4, key cell cycle regulators, are often overexpressed in melanomas, leading to uncontrolled cell proliferation." (PMID 40867317, 2025). "Our results show that optimal inhibition of tumor growth in the B16F10 melanoma model can be obtained with co-inhibition of CDK4/6 and CDK2 along with SX-682." (PMID 40904502, 2025). "Two studies revealed that melanomas resistant to CDK4/6i treatment exhibited higher levels of MDM2 and MDM4 proteins compared to treatment-sensitive cells." (PMID 40282469, 2025). "MEKi and CDK4/6i combination therapy was found to increase the capacity of melanoma cells to present antigens and recruit cytotoxic CD8+ T cells to the tumor." (PMID 40282469, 2025). "This strategy (CDK4/6 inhibition with immunotherapy) is currently being explored in melanoma in the PLATforM clinical trial (NCT03484923)." (PMID 40282469, 2025). "CDK4 had 0 carriers with melanoma, while VHL had 1 carrier with kidney cancer, and the OR was non-significant (3.5 [0.49, 25.4], p = 0.21)." (PMID 40073867, 2025). "In this study, we aimed to evaluate the anti-cancer efficacy of ArcA as a cyclin D1/CDK4 inhibitor in metastatic melanoma cells, specifically using highly metastatic derivatives that had metastasized to the lung and brain." (PMID 39948552, 2025). "Palbociclib, a CDK4/6 inhibitor that blocks cell cycle progression, has also shown promise in melanoma treatment." (PMID 40297440, 2025). "Despite these encouraging preclinical studies, early clinical studies in melanoma evaluated CDK4/6is as monotherapy and demonstrated limited efficacy." (PMID 40282469, 2025). "In a murine colon cancer model, CDK4 knockout along with antibodies against programmed death-ligand 1 (PD-L1) enhanced antitumour immune responses, whereas in melanoma model mice, CDK4/6 inhibition reversed the resistance to ICIs." (PMID 41388212, 2025).
melanoma (continued). "Conversely, the depletion of macrophages and DCs was observed in melanoma patients as a side effect of the continuous administration of a therapeutic regimen including CDK4/6 inhibitors." (PMID 41388212, 2025). "Variants in CDKN2A, CDK4, and MC1R—such as G101W, A148T, and R24C—have been associated with melanoma in populations from Poland, Spain, and the United Kingdom (UK) as well as in Brazilian and Austrian populations." (PMID 40429816, 2025). "Unfortunately, CDK4/6 inhibitors (CDK4/6is) have demonstrated limited clinical effectiveness in melanoma to date." (PMID 40282469, 2025). "On that note, we have previously examined the response of seven human melanoma cell lines and five melanoma patient-derived xenografts to treatment with a CDK4/6 inhibitor alone or in combination with an MDM2 inhibitor." (PMID 40904502, 2025). "Most were gain-of-function mutations (e.g., E545K, H1047R), which are known to confer resistance to MEK and CDK4/6 inhibitors in NRAS-mutant melanoma." (PMID 40652269, 2025). "Germline variants in CDKN2A, CDK4, BAP1, POT1, ACD, TERF2IP, and TERT have been identified as high-penetrance variants associated with melanoma development." (PMID 40429816, 2025). "For example, CDK4 has been hyperactivated in up to 90% of melanoma cases and occurs through various mechanisms, including mutation of CDK4 (R24C)." (PMID 39593745, 2024). "These inhibitors work by targeting the CDK4/6 pathway, which is frequently altered in melanoma, leading to uncontrolled cell proliferation." (PMID 39200315, 2024). "The researchers pointed out that a knockdown of the CDK4 gene delays G1/S transition in the oral mucosal melanoma cell line." (PMID 39598629, 2024). "We observed only very few structural genomic aberrations in primary melanomas that arose spontaneously in untreated Hgf-Cdk4 mice." (PMID 38360887, 2024). "In senescent melanoma, CDK4/6 inhibitors increase the secretion of IFN‐γ and IFN‐β, attracting infiltrating CD8+ T cells into the TME and sensitising tumour cells to immune checkpoint inhibitors." (PMID 39270064, 2024). "In the context of NRAS mutant superficial spreading melanoma, network modeling of tumor cells treated with MEKi has identified CDK4 as a key driver of therapy resistance." (PMID 38066089, 2024). "Mutations or deletions in CDKN2A/B genes and amplification of CDK4 are commonly observed in melanoma, contributing to uncontrolled cell proliferation and tumor growth." (PMID 38982214, 2024). "We have systematically collated data from clinicaltrials.gov concerning trials involving CDK4/6 inhibitors in melanoma." (PMID 38469735, 2024). "The benefits of using Bcl-3 blocking instead of recently approved CDK4/6 inhibitors are that targeting Bcl-3 will only affect metastatic melanoma cells, while CDK4/6 inhibitors affect all actively dividing cells." (PMID 38238702, 2024). "Targeting CDK4 as potential therapeutic opportunities in melanoma has been of interest for several years." (PMID 38807144, 2024). "On the other hand, a study conducted by Vanderbilt University Medical Center explored how MDM2 influences resistance to CDK4/6 inhibitors in melanoma treatment." (PMID 39200315, 2024). "In recent years, CDK4/6 inhibitors such as palbociclib, abemaciclib and dalpiciclib have been successfully tested on mucosal melanoma cell lines and xenograft mouse models." (PMID 39598629, 2024). "Mutated BRAF exerts exquisite control over MITF, which regulates the expression of key cell cycle facilitators, such as CDK2 and CDK4, stimulating melanoma cell proliferation, survival, and phenotype switching from proliferative and invasive states." (PMID 39735251, 2024). "In the Hgf-Cdk4 model, incipient melanomas were selected for amplifications of chromosome 6 in the region harboring the gene encoding the Met receptor." (PMID 38360887, 2024).
melanoma (continued). "To test the clinical relevance of targeting CDK4 for treating melanoma, we collected PDCs from patients who belong to S-II and S-III and treated them with a CDK4 inhibitor." (PMID 39039072, 2024). "In previous work, we established the genetically engineered Hgf-Cdk4 mouse melanoma model, in which mice spontaneously develop melanocytic nevi and metastatic melanoma in a stepwise progression." (PMID 38360887, 2024). "Preclinical and clinical studies validate CDK4 as a potential target for therapeutic intervention in melanoma patients." (PMID 38807144, 2024). "In melanoma, CDK4/6 inhibitors, especially the oral inhibitor palbociclib, have been applied in combination with other inhibitors, which are targeted at BRAF and MEK." (PMID 39598629, 2024). "To analyze the occurrence of structural aberrations in the Hgf-Cdk4 melanoma model, we performed comparative genomic hybridization analyses of primary melanomas, serial transplants, and the HCmel3 and HCmel12 cell lines." (PMID 38360887, 2024). "Several high-penetrance melanoma susceptibility genes, including CDKN2A and CDK4, are associated with familial melanoma syndromes characterized by an autosomal dominant inheritance pattern." (PMID 39200315, 2024). "The inclusion of CDK4/6 inhibitors and PROTACs targeting CDK4/6 in melanoma treatment regimens represents a significant advancement in the management of this aggressive cancer." (PMID 39200315, 2024). "Primary melanomas from UVB/DMBA-treated Hgf-Cdk4 mice showed initial large chromosomal gains and losses that markedly increased during serial transplantation and in established cell lines." (PMID 38360887, 2024). "A study of 514 acral melanomas revealed that alterations in the CDK4 pathway were frequent and that these alterations promoted G1 to S cell cycle transition and tumor progression." (PMID 38528036, 2024). "For instance, TIS fibroblasts induced by the CDK4/6 inhibitor palbociclib in an immunocompetent murine model promoted not only melanoma cell proliferation but also the accumulation of myeloid-derived suppressor cells." (PMID 39126015, 2024). "This recruitment facilitates the ubiquitination and proteasomal degradation of CDK4/6, suppressing melanoma cell proliferation." (PMID 38410129, 2024). "Excitingly, there was a significant reversal in drug resistance after receiving intermittent treatment with CDK4/6is in a patient with advanced melanoma who exhibited resistance to immunotherapy." (PMID 39593745, 2024). "A family history of CM poses the highest risk for the development of melanoma and germline mutations in some high-penetrance CM susceptibility genes have been described, namely in CDKN2A, CDK4, MITF, TERT, BAP1, and POT1." (PMID 38730639, 2024). "Melanoma is an attractive target for CDK4/6 inhibitors because the p16INK4a/Cyclin D1-CDK4/6/RB pathway is dysregulated in the majority of melanomas." (PMID 38565978, 2024). "A DMS analysis performed in the melanoma Meljuso cell line with the ATP-competitive CDK4/6 inhibitor palbociclib uncovered hotspot residues in CDK4 and CDK6 involved in resistance, which were also confirmed in ERK2." (PMID 38255778, 2024). "Common aberrations, which have influence on melanoma development, include CDKN2A (p16 coding gene) mutations and deletions as well as CDK4/6 genes and CCND1 (cyclin D1 coding gene) amplification." (PMID 39598629, 2024). "An innate CDK4/6-driven transcriptional program that reduced the physical interactions between melanoma cells and T cells, leading to the exclusion of T cells in melanoma tumours was also identified using scRNA-seq analysis." (PMID 38241976, 2024). "Currently, various Cdk4/6 inhibitors are entering clinical trial stages for the treatment of different types of cancers, including leukemia, melanoma, and lung cancer." (PMID 38701314, 2024). "Here, we report the evolutionary trajectory of genomic alterations that drive primary cutaneous and serially transplanted melanomas of Hgf-Cdk4 mice." (PMID 38360887, 2024).